IL6 (interleukin 6)
Diseases named in the same sentence as IL6 in open-access papers (continued):
Sharing a sentence is not in itself a finding about the gene and the disease.
cancer (continued). "IL-6 plays a role in inflammation, acute-phase response, and development of cachexia, acts as a paracrine and autocrine growth factor for cancer cells, and inhibits radio- and chemotherapy-induced apoptosis of PC cells." (PMID 23840582, 2013). "IL-6 contributes to ovarian cancer metastasis via a complex multistep process involving the adhesion, migration and invasion of cancer cells." (PMID 23593315, 2013). "The STAT3 activation by IL-6 is well-documented to support growth, survival and metastasis of human cancer cells." (PMID 23658720, 2013). "Positive staining for p-STAT3 was evident in 47% of the 173 cancer specimens, and a significant positive correlation was found in cancer specimen that expressed IL-6 and p-STAT3." (PMID 23561329, 2013). "IL6 is an interleukin that plays a key role in the pathophysiology of several cancers and various inflammatory disorders of the immune system." (PMID 23874655, 2013). "IL-6 has been found elevated in several cancers and cancer cell lines including colon, breast, gastrointestinal tract, lymph nodes, skin, lung, ovary, pancreas, prostate, and kidney, and it is known to promote angiogenesis." (PMID 23819063, 2013). "Interleukin-6 (IL-6) is produced by cancer cells (including PC), macrophages, lymphocytes, and endothelial cells." (PMID 23840582, 2013). "Previously study revealed that upon IL-6 treatment, Mcl-1 was rapidly up-regulated peaking at 4–8 h in human cancer cells." (PMID 23825534, 2013). "IL-6 plays a role in inflammation and the acute-phase response, acts as a paracrine and autocrine growth factor for cancer cells, and inhibits radio- and chemotherapy-induced apoptosis of PC cells." (PMID 23840582, 2013). "The caveat for this paracrine signaling is that cancer cells should express sufficient receptor machineries to recognize the increased IL-6 supply from the microenvironments." (PMID 24021059, 2013). "Further investigations are needed to clarify how EGFR-TKI regulates IL-6 production in cancer cells." (PMID 23592411, 2013). "Because STAT3 is one of the targets for anti-cancer drug resistance, most of investigations have been only focused on how IL-6 regulates the drug resistance in EGFR-TKI-treated cancer cells." (PMID 23592411, 2013). "Agents that are able to inhibit IL-6 are of great value for immunotherapies against TNBC and other IL-6-producing cancers." (PMID 24156030, 2013). "Il-6 is also known to have pro-angiogenic and pro-tumorigenic inflammatory properties in many cancer types." (PMID 23520493, 2013). "Treatment of human carcinoma KB cells with Egr1 siRNA led to a decrease in IL6 and IL8 promoter activation, and Egr1 was found to bind to the promoters of both interleukins." (PMID 23342084, 2013). "The transcription of several key inflammatory factors, including IL1β, IL6 and TGFβ1, was induced in the carcinomas of both mice." (PMID 23526950, 2013). "Alternatively, CRP is a component of the acute- phase response mainly induced by interleukin-6, and thus has the potential to enhance or inhibit the proliferation of carcinoma cells." (PMID 23497335, 2013). "Among them, interleukin-1β (IL-1β), tumor necrosis factor-α (TNF-α), lymphotoxin-α (LT-α), interleukin-6 (IL-6), and interleukin-12 (IL-12) are potent pro-inflammatory cytokines with a relevant role in both cancer development and progression." (PMID 23029430, 2012). "Taken together, these findings suggest hochuekkito ameliorated experimental cancer cachexia in mice through the inhibition of macrophage-derived cytokine production, especially IL-6." (PMID 23326296, 2012). "In summary, serum IL-6 was a risk factor of all-cause, CVD, cancer, and liver-related mortality in community-dwelling older adults." (PMID 22514624, 2012).
cancer (continued). "Taken together, these studies indicate CAFs as important components of a cancer stem cell niche providing regulating factors such as IL-6, BMP antagonists, and factors activating canonical and non-canonical Wnt signaling." (PMID 22509805, 2012). "In these community-dwelling older men and women with a median follow-up of 15.3±10.6 years, increased serum IL-6 levels were associated with an increased risk of all-cause, CVD, cancer, and liver-related mortality." (PMID 22514624, 2012). "Tocilizumab, an anti-IL-6 therapy has been used in rheumatoid arthritis, cancer therapy, and cancer-related anorexia." (PMID 22933833, 2012). "We also investigated the effects of hochuekkito on the production of proinflammatory cytokines including IL-6 from C26 adenocarcinoma cells and two macrophage cell lines in vitro, and discussed the significance of hochuekkito in treatment of cancer cachexia." (PMID 23326296, 2012). "In community-dwelling older adults, serum IL-6 is associated with all-cause, CVD, cancer, and liver-related mortality." (PMID 22514624, 2012). "Cancer cells that are exposed to IL-6 or secrete the cytokine as an autocrine factor show increased invasiveness." (PMID 22745766, 2012). "Our report indicates that IL-6 can induce an epigenotype switch at an imprinted locus in human cancers and adds further rationale to IL-6 targeting." (PMID 23110045, 2012). "Both, TNF-α and IL-6 levels increased from Group 1 to Group 3 corresponding to increasing age and stages of cancer progression." (PMID 22427843, 2012). "Serum IL-6 is associated with an increased risk of all-cause, CVD, cancer, and liver-related mortality in older adults and 2)." (PMID 22514624, 2012). "Activation of STAT signaling, via IL-6, is known to induce cancer cell proliferation, survival, and invasion, while suppressing host antitumour immunity." (PMID 22701472, 2012). "In this study, elevated Socs3 and Il-6ra likely resulted from the action of circulating IL-6 on skeletal muscle during cancer cachexia, as the rise in gene expression appeared to follow elevation of circulating IL-6." (PMID 22361433, 2012). "Together, N-2 strongly inhibited the NF-κB reporter and its downstream cytokine IL-6, a property that provides a rationale for chemoresistant cancer therapy using N-2." (PMID 23028510, 2012). "These lines of evidence indicate that proinflammatory cytokines such as IL-6 play pivotal roles in the pathogenesis of cancer cachexia and are potential targets for the therapy of cancer patients with a cachectic condition." (PMID 23326296, 2012). "Targeting STAT3 as a potential cancer therapy has been extensively investigated, and recently new small-molecule inhibitors have been developed which show to inhibit IL-6-induced STAT3 activation and nuclear translocation in HCC cells." (PMID 22470194, 2012). "In many tumors and cancer cells, constitutive activation of STAT3 is IL-6 dependent, through either autocrine or paracrine signaling, which seems to be widely expressed in cancer cell lines." (PMID 22662257, 2012). "After adjusting for age, sex, BMI, total cholesterol, HDL, serum glucose, systolic blood pressure, smoking status, and alcohol use, serum IL-6 remained independent risk factor of all-cause, CVD, cancer, and liver-related mortality." (PMID 22514624, 2012). "Several IL-6 signaling pathway-related genes including STAT3 are also associated with migration and invasion of cancer cells." (PMID 22745766, 2012). "It has been shown previously that cancer cells expressing PD-L1 on their surface secrete immunosuppressive cytokines Galectin-1, IL-6, IL-10, and TGF-β, which can inhibit cytotoxic CD8+ T cells." (PMID 22496728, 2012). "In view of the important role of IL-6 in the malignant features of cancer, we were interested to explore the relationship between IL-6 and BrCSCs." (PMID 22134360, 2012).
cancer (continued). "IL-6 plays decisive roles in the inflammation, immune response, and hematopoiesis, thus therapeutic targeting of IL-6 and its receptor in cancer has strong biologic rationale." (PMID 22811589, 2012). "Compatible with this idea, ACTH responses were diminished from the beginning to the end of studies of patients with cancer injected daily with IL-6 for 7 or 21 days." (PMID 22894827, 2012). "In this study, we investigate the predictive value of IL-6 levels for all-cause, CVD, cancer, and liver-related mortality using a large, prospective cohort of older men and women in Southern California." (PMID 22514624, 2012). "It is well known that IL-6 production and increased circulating level have been emerged as biomarkers of poor prognosis in many human cancers." (PMID 22583829, 2012). "Multivariable-adjusted Cox proportional hazards regression analyses were used to examine the association between serum IL-6 as a continuous (log transformed) variable with all-cause, CVD, cancer, and liver-related mortality." (PMID 22514624, 2012). "The IL6 expression was higher in OSCC cancer cells than in normal tissues and IL6 appeared to be involved in the tumorigenesis of OSCC." (PMID 23185547, 2012). "Increased skeletal muscle mRNA expression of Suppressor of Cytokine Signaling (Socs) 3 and the IL-6 receptor indicative of active IL-6 signaling was seen in skeletal muscle of mice bearing the Colon 26 (C26) carcinoma." (PMID 22361433, 2012). "An investigation into the levels of IL-6 in terminally ill cachectic cancer patients found that IL-6 levels were dramatically elevated one week prior to death." (PMID 21832306, 2011). "Our findings show that IL-6 apparently mediates both the hepatic and skeletal muscle acute phase response through STAT3 activation in cancer, thereby positioning the IL-6/STAT3 pathway as a potentially important target to reduce skeletal muscle wasting." (PMID 21799891, 2011). "STAT3 activation has also been observed in muscle in other experimental models of cancer cachexia with high IL-6, namely ApcMin/+ mice." (PMID 21799891, 2011). "Second, they establish a molecular link between the observations of high IL-6, increased acute phase response proteins and muscle wasting in cancer." (PMID 21799891, 2011). "IL-6 is a multifunctional cytokine which is known to affect proliferation, apoptosis and angiogenesis in cancer." (PMID 22136659, 2011). "On the other hand, IL-6 promotes cancer cell proliferation while also inhibits apoptosis of cancer cells through activation of signal transducer and activator of transcription 3 (Stat3)." (PMID 22162712, 2011). "Through IL-6/STAT3 activation, skeletal muscle is induced to synthesize acute phase proteins, thus establishing a molecular link between the observations of high IL-6, increased acute phase response proteins and muscle wasting in cancer." (PMID 21799891, 2011). "The post-EMT cell line MDA-MB-231 differed to the other post-EMT, basal and luminal cell lines in being the only cancer cell line showing IL-6 and G-CSF cytokine and IP-10 chemokine expression." (PMID 21535870, 2011). "The molecular links leading to IL-6 production in epithelial cancer cells, which are correlated with distant metastasis and cancer stem cell-like properties, are currently under active investigation." (PMID 21967801, 2011). "For example, CEBPB (NFIL6) is a principal effector of cyclin D1 activity in human cancer and an enhancer of e.g. IL-6 transcription, which plays an important role in the acute phase response." (PMID 21799770, 2011). "We sought to mimic the high serum IL-6, acute phase response and muscle wasting of patients with cancer cachexia." (PMID 21799891, 2011). "There is a delicate balance that must be achieved between using IL-1 and IL-6 for therapeutic purposes, while also abrogating the cancer-promoting characteristics of each cytokine." (PMID 21765834, 2011).
cancer (continued). "As one of the core cytokines, interleukin-6 (IL-6), is produced by lymphocytes, mononuclear cells, fibroblasts, vascular endothelial cells, and some cancer cells, primarily in autocrine and paracrine secretions." (PMID 21345194, 2011). "The possible role of the inflammatory cytokines in the development and spread of cancer cells led us to examine the involvement of leptin in the production of IL-1a, IL-1b, IL-6 and TGF-β1 by human HCC cells." (PMID 20723213, 2010). "Collectively, these results confirm that both PI3-K/Akt and MEK/Erk pathways contribute to the regulation of IL-6 autocrine production in cancer cells." (PMID 21122157, 2010). "The pleiotropic cytokine interleukin-6 (IL-6) is a major activator of Stat3; IL-6 stimulates the formation of tyrosine-phosphorylated Stat3 (p-Stat3) in cancer cells." (PMID 20482858, 2010). "Instead, the IL-6 downstream signal pathways, including Jak2/Stat3, co-cooperated to control the IL-6 autocrine production in the cancer cells we tested." (PMID 21122157, 2010). "Collectively, our data show that Stat3 is one of the pivotal factors contributing to the regulation of autocrine production of IL-6 in cancer cells." (PMID 21122157, 2010). "In the pharmacological experiments, Akt and Erk inhibitors significantly decreased IL-6 production in various cancer cells." (PMID 21122157, 2010). "Recently, it has been reported that expression of IL-6 is correlated with prognosis in various cancer patients." (PMID 20667141, 2010). "IL-6 activates a feed-forward loop leading to increased STAT3 activation in cancer and inflammatory cells, where STAT3 promotes polarization of innate immunity towards immuno-suppressive alternate activation." (PMID 21059221, 2010). "Recent studies have shown that it decreases interleukin-6 (IL-6) production in keratinocytes and KB cancer cells." (PMID 20507639, 2010). "To confirm that Stat3 regulated IL-6 expression in cancer cells, we transiently transfected AS2 cells with Stat3 siRNA to knock-down the expression of Stat3." (PMID 21122157, 2010). "It has been shown that cancer cells resistant to chemotherapeutic agents express elevated levels of IL-6, and the IL-6 contributes to the drug resistance of cancer cells." (PMID 21122157, 2010). "PGN-SA induced phosphorylation of TAK1 and IκB in the TLR2-NF-κB pathway of the cancer cells and stimulated IL-6 and TGF-β secretion in MDA-MB-231 cells." (PMID 20520770, 2010). "Other studies reviewed the correlation between IL-6 before radio-chemotherapy and cancer therapy resistance, including the possibility of metastases." (PMID 20184737, 2010). "The therapeutic significance of the blockade of IL-6 production or IL-6 signalling, which includes trans-signaling through the IL-1–IL-6 cascade or sIL-6R, in the cancer microenvironment remains to be clarified in future investigations." (PMID 20823887, 2010). "Many studies have suggested that IL-6 signal transduction is intimately involved in cancer progression." (PMID 20823887, 2010). "Inflammation in cancer leads to elevated IL-6 production by two mechanisms: Src-mediated activation of NF-κB leading to transactivation of the IL-6 gene, and rapid degradation of let-7 miRNA, which is a direct inhibitor of IL-6 expression." (PMID 20204067, 2010). "This study was designed to determine the role of Jak2/Stat3 pathway in the regulation of IL-6 autocrine production in cancer cells." (PMID 21122157, 2010). "Different cancer cells utilize different combinations of signals to orchestrate IL-6 autocrine production." (PMID 21122157, 2010). "We compared our findings on IL-6 and TLR-4 in human tissues with inflammation-tracking in a mouse model of experimentally-induced colitis-associated cancer in Tir8 deficient mice." (PMID 21059221, 2010). "It has been shown that cancer cells resistant to chemotherapeutic agents express elevated levels of IL-6." (PMID 21122157, 2010).
cancer (continued). "IL-6 is a downstream product of activation of NF-κB, a fundamental molecular hub linking inflammation and cancer." (PMID 21059221, 2010). "In AS2 derived cells, resistance to paclitaxel was positively correlated with Stat3 activation status and the expression of IL-6, which is commonly secreted in drug resistant cancer cells." (PMID 21122157, 2010). "We found that the NF-κB pathway was the most important, but not an essential, regulator of IL-6 secretion in the tested cancer samples and that Jak2/Stat3 pathway contributed substantially to the regulation of IL-6 secretion in many cancer samples." (PMID 21122157, 2010). "IL-6 levels are increased in most epithelial tumors, and high serum IL-6 levels have been found to correlate with a poor clinical prognosis in patients with diverse carcinomas (renal, ovarian and colorectal)." (PMID 21059221, 2010). "An overproduction of IL-6 following irradiation of patients attained of various cancers had been previously suggested." (PMID 19956602, 2009). "Top biological functions found to be regulated by IL-6 include cancer (61 genes), cellular growth and proliferation (54 genes), cell death (47 genes), cell-to-cell signalling and interaction (46 genes), tissue development (45 genes) and others." (PMID 19239705, 2009). "The relative expression of ANXA1 in the CD26+ cancer cells vs. luminal cells was also decreased in G4 compared to G3, whereas relative IL6 expression was increased." (PMID 20021671, 2009). "There are supportive evidences that cadmium increases IL-6 production and Akt activation in cancer cell." (PMID 19523218, 2009). "Production of high levels of IL-6 is often correlated with resistance to cytotoxics or ionizing radiations, in cancer cell lines as in various cancer patients." (PMID 19956602, 2009). "The behaviour of cytokines IL-6 and IL-8 has also been examined extensively, particularly in cancer patients." (PMID 19259415, 2008). "But, it should be noted that the levels (pg ml−1) of the cytokines observed in cancer patients in this study is approximately 100-fold lower than the 10 ng ml−1 concentrations of IL-6 and TGF-β required to significantly downregulate CYP2C19 mRNA in vitro." (PMID 18854824, 2008). "Both IL-6 and TNF-α levels were increased significantly in the TB group, which confirmed the role of TNF-α besides IL-6, in the pathogenesis of cancer cachexia in the C26 model." (PMID 19018259, 2008). "Specifically, IL-6 regulates theexpression of antiapoptotic genes and mediates cell cycle progression.Elevated IL-6 levels have been liked to the pathogenesis of cancer." (PMID 19277104, 2008). "IL-6 is also able to inhibits cell-cell adhesion and to promote spreading of cancer cells and to inhibit T-cell proliferative response." (PMID 17953739, 2007). "The greatest differences in expression between normal breast tissue and carcinoma occurred in IL-8, MCP-1 and MIP-1β, which were 60-fold more abundant in carcinoma than in healthy breast, followed by IL-6, which was about 14-fold overexpressed in carcinoma." (PMID 17261184, 2007). "Proinflammatory cytokines were significantly overexpressed (interleukin (IL)-1β, IL-6, IL-8 and tumour necrosis factor-α) both at mRNA and protein levels in the cancer specimens compared with mucosa from controls." (PMID 17088911, 2006). "For example it has been shown that vascular endothelial growth factor (VEGF), IL-1β and IL-6 are upregulated in serum of cancer patients and that VEGF and IL-1β can increase Cx43 expression." (PMID 15987459, 2005). "Over a 4 h feeding period, the areas under the curve for glucose, cortisol and interleukin-6 were greater (P<0.05), but less for leptin in the cancer group (P<0.05)." (PMID 15026790, 2004). "The molar ratio (molecular weights of leptin and interleukin-6 are 16 and 26 kDa, respectively) of the areas under the curve for leptin and interleukin-6 was approximately 1000-fold greater in the weight-losing cancer group (P<0.01)." (PMID 15026790, 2004).